MIR136 (microRNA 136)
Synonyms: hsa-mir-136; MIRN136; miRNA136; mir-136
Gene: MicroRNA gene on chromosome 14 (100,884,702 to 100,884,783, forward strand). Ensembl gene ENSG00000207942.
Gene Ontology:
Biological process: miRNA-mediated post-transcriptional gene silencing
Cellular component: RISC complex
Homologues: Orthologues: chimpanzee ptr-mir-136 (100% identical), macaque mml-mir-136 (100% identical), pig ssc-mir-136 (99% identical), rat Mir136 (99% identical).
Diseases named in the same sentence as MIR136 in open-access papers:
MIR136 is named in the same sentence as 1 disease in open-access papers, as found by Europe PMC text mining. Sharing a sentence is not in itself a finding about the gene and the disease. The quoted sentences say what the papers report.
tumor (1 paper, 2017). "We thus confirmed MIR205-5p and MIR136-5p expression in tumor tissue: MIR205-5p expression was elevated in tumor compared to normal tissue; and MIR136-5p expression was reduced in tumor compared to normal tissue for most of analyzed samples." (PMID 28704519, 2017).